CDK12 (cyclin dependent kinase 12)
Diseases named in the same sentence as CDK12 in open-access papers (continued):
Sharing a sentence is not in itself a finding about the gene and the disease.
melanoma (continued). "Our results show that inhibition of these pathways strongly synergize with CDK12 inhibitors to inhibit melanoma growth, suggesting potential combinations for the treatment of melanoma patients." (PMID 36309522, 2022). "We characterized the transcriptional program controlled by CDK12 in melanoma and found that CDK12 regulates gene expression based on gene length." (PMID 36309522, 2022). "More work will be required to increase the selectivity of CDK12 inhibitors, as well as their efficacy in vivo, to evaluate their full potential as melanoma therapeutics." (PMID 36309522, 2022). "Consistent with this, we found that melanoma cells are more sensitive to CDK12 inhibition than melanocytes, suggesting that CDK12 activity is particularly important for the maintenance of genomic stability in melanoma." (PMID 36309522, 2022). "Together, these data demonstrate that combinations of CDK12 and JNK inhibitors are synthetic lethal for BRAF-mutated melanoma cells." (PMID 36309522, 2022). "Together, these data indicate that the combined inhibition of CDK12 and IKKβ results in significant reductions in melanoma growth in a mouse model." (PMID 36309522, 2022). "Collectively, these results demonstrate that CDK12 inhibition results in the specific upregulation of AP-1 and NF-κB pathways in BRAF-mutated melanoma cell lines." (PMID 36309522, 2022). "To measure the kinase activity of CDK12, we performed in vitro kinase reactions using endogenous CDK12 immunoprecipitated from A375, a BRAF-mutated melanoma cell line." (PMID 36309522, 2022). "Together, these data demonstrate that combinations of CDK12 and IKKβ inhibitors are synthetic lethal for BRAF-mutated melanoma cells." (PMID 36309522, 2022). "In complement to CDK12 kinase activity, we measured RPB1 phosphorylation and the expression of CDK12 target genes in BRAF-mutated melanoma cell lines." (PMID 36309522, 2022). "To validate the regulation of these pathways by CDK12, we treated both melanoma cell lines with increasing concentrations of two CDK12 inhibitors (THZ531 and SR-4835)." (PMID 36309522, 2022). "We found that CDK12 inhibition upregulates the expression of AP-1 and NF-κB gene targets, and show that inhibition of these pathways sensitizes melanoma cells to CDK12 inhibition in vitro and possibly in vivo." (PMID 36309522, 2022). "In this study, we found that CDK12 is active in melanoma and necessary to maintain the expression of genes involved in the DNA damage response." (PMID 36309522, 2022). "We find that melanoma cells harbor constitutively high CDK12 activity, and that its inhibition decreases the expression of long genes containing multiple exons, including many genes involved in DNA repair." (PMID 36309522, 2022). "Our results show that the RAS/MAPK pathway promotes CDK12 phosphorylation and activation, and that CDK12 inhibition impairs melanoma cell survival and proliferation." (PMID 36309522, 2022). "Of note, both melanoma and non-melanoma skin cancers show exceptionally high frequencies of CDK12 and CDK13 mutations across all cancers." (PMID 41491919, 2026). "CDK12 plays an important role in the growth of cancers driven by dysregulated transcription factors, such as MYC (neuroblastoma) and the EWS–FLI1 fusion (Ewing sarcoma), or in melanoma driven by activating mutations in BRAF." (PMID 38104154, 2023). "Compared to melanocytes, we found that several BRAF-mutated melanoma cell lines display high levels of RPB1 Ser2 and Ser5 phosphorylation, which could be indicative a higher CDK12 activity." (PMID 36309522, 2022). "While CDK12 is a potential therapeutic target for melanoma, first-line treatments with trametinib and dabrafenib, or a combination thereof, appear much more efficient to inhibit melanoma growth in mice." (PMID 36309522, 2022).
melanoma (continued). "Combined inhibition of CDK12 and MAPK signaling produces synthetic lethality in melanoma cell lines and murine models, highlighting the potential of dual pathway targeting to overcome resistance to BRAF and MEK inhibitors." (PMID 41491919, 2026). "In BRAF-mutated melanoma, CDK12 activity drives tumor proliferation and genomic stability, while the CDK12/13 inhibitor SR-4835 inhibits DDR gene expression, induces DNA damage, and impairs melanoma growth." (PMID 40075638, 2025).
triple-negative breast carcinoma (14 papers, 2014 to 2024). An invasive breast carcinoma which is negative for expression of estrogen receptor (ER), progesterone receptor (PR), and human epidermal growth factor receptor 2 (HER2). "For this, we performed RNA sequencing (RNA-seq) in MDA-MB-231 cells, choosing triple-negative breast cancer cells as the relevant therapeutic context for CDK12/13–cyclin K inactivation." (PMID 37679459, 2024). "In addition, Dinaciclib was also shown to inhibit CDK12 in triple-negative breast cancer cells and to sensitize them to PARP inhibitors in CDK12-dependent manner." (PMID 37599362, 2023). "Moreover, a recent study reported that a new selective CDK12/13 inhibitor (SR‐4835) also displayed synthetic lethality in combination with DNA‐damaging agents in triple negative breast cancer cells." (PMID 34092037, 2021). "In models of triple-negative breast cancer (TNBC) which is an invasive breast carcinoma subgroup, dinaciclib as a CDK12 inhibitor cuts down the expression of HR gene in BCRA wild-type TNBC cells." (PMID 39318358, 2024). "In addition, in triple-negative breast cancer (TNBC), on account of the deletion of CDK12, it can changeover both De nova PARPi resistance and acquired PARPi resistance, regardless of in BRCA wild-type or mutated models." (PMID 39318358, 2024). "Indeed, previous studies showed that CDK12 inhibition by dinaciclib, a pan‐CDK inhibitor, sensitised to PARPi triple negative breast cancer cells that are wild type for BRCA1/2." (PMID 34092037, 2021).
serous ovarian carcinoma (13 papers, 2013 to 2024). "CDK12 loss-of-function mutations are detected in malignancies with highly unstable genome, such as high-graded serous ovarian carcinomas and metastatic-castration resistant prostate cancers." (PMID 35163134, 2022). "CDK12 mutations and amplification have been recently reported in different types of malignancies, including loss-of-function mutations in high-grade serous ovarian carcinomas, and that has led to assumption that CDK12 is a tumor suppressor." (PMID 29090014, 2017). "For example, CDK12 is a tumor suppressor in high-grade serous ovarian carcinoma, wherein its recurrent loss-of-function mutations prompt downregulation of HR genes, impairment of DNA double-strand break (DSB) repair via HR and cellular sensitivity to PARP inhibitors." (PMID 37811895, 2023). "Finally, our work provides new insights into the tumor suppressive role of CDK12 in the genesis of cancers with biallelic CDK12 inactivation such as in high-grade serous ovarian carcinoma." (PMID 37811895, 2023). "In addition, this panel is targeting “hotspot” region of genes that are frequently mutated in human cancer thus other infrequently altered genes but of significance to serous ovarian cancers might have been excluded such as ARID1A, BRCA1, BRCA2, CSMD3, NF1, CDK12, FAT3 and GABRA6." (PMID 25404506, 2014).
metastatic prostate carcinoma (12 papers, 2020 to 2025). A carcinoma that arises from the prostate gland and has spread to other anatomic sites. "It is believed that genomic instability caused by CDK12 deletion or mutation contributes to metastatic prostate cancer." (PMID 40361480, 2025). "Conversely, XGBoost-derived models showed strong performance including an area under the curve of 0.99, 0.99 and 1.00 for identifying BRCA2, CDK12, and mismatch repair deficiency in metastatic prostate cancer." (PMID 36914848, 2023). "It is considered that loss or mutation of CDK12 leads to genomic instability, which contributes to metastatic prostate cancer." (PMID 32570740, 2020). "Because these genes frequently have copy number gain in metastatic prostate cancer, it is uncertain whether the copy number gains of our small cohort were associated with CDK12 alterations." (PMID 36271301, 2022). "KOURO_31-408, a case of metastatic prostate cancer with an aggressive course, showed a copy number plot similar to that previously reported as typical of CDK12 biallelic loss, and the small copy number gains might reflect focal tandem duplications (FTDs)." (PMID 36271301, 2022). "The deletion rate of CDK12 in patients with metastatic prostate cancer is approximately 3%–7%." (PMID 38089758, 2022).
colorectal cancer (11 papers, 2022 to 2024). A primary or metastatic malignant neoplasm that affects the colon or rectum. "Demonstrated that the targeted degradation of CCNK/CDK12 complex is a druggable vulnerability of colorectal cancer." (PMID 38459430, 2024). "On the other hand, degradation of CCNK/CDK12 in colorectal cancer inhibits cancer cell proliferation and growth in vivo." (PMID 36374405, 2023). "In this study, we selectively inhibited CDK12 by pharmacological and chemical genetic means in a well-established cell line model of colorectal cancer to uncover mechanistic and functional aspects of the induced transcriptome." (PMID 37811895, 2023). "In the present study, CDK12 overexpression was associated with higher survival rate, while patients with downregulated expression of CDK10 and 16 exhibited lower OS, suggesting that CDK10/16 and CDK12 can be used as prognostic biomarkers for colorectal cancer patients." (PMID 35814446, 2022). "Targeting CCNK/CDK12 degradation might regulated colorectal cancer." (PMID 36463205, 2022). "Colorectal cancer patients with high expression levels of CDK 5/10/16 achieved lower OS, while high expression of CDK12 increased OS, hinting that CDK 5/10/12/16 can be utilized as prognostic biomarkers." (PMID 35814446, 2022). "There were no significantly discordant genes between primary colorectal cancer and CRLM; however, CDK12, ERBB3 and DICER1 were exclusively mutated in CRLM." (PMID 37057593, 2023).
Ewing sarcoma (11 papers, 2019 to 2026). A small round cell tumor that lacks morphologic, immunohistochemical, and electron microscopic evidence of neuroectodermal differentiation. "Prior studies demonstrated that EWS::FLI1 is associated with high replication stress states, in which CDK12/13 mediates the transcriptional activity of DNA damage repair in fusion-positive Ewing sarcoma." (PMID 40760094, 2025). "Wildtype CDK12 has vulnerability in EWS/FLI-positive Ewing sarcoma cells treated with THZ531, leading to downregulation of HRR genes." (PMID 35163134, 2022). "THZ531, a covalent and potent inhibitor of CDK12 and 13, has been shown to be effective in Ewing’s sarcoma." (PMID 35163134, 2022). "Currently, treatment of Ewing sarcoma mainly uses CDK12 inhibitors THZ1 and THZ531, which impair DNA damage repair in an EWS/FLI-dependent manner." (PMID 32570740, 2020). "Furthermore, CDK12 specific inhibition in EWS/FLI-positive Ewing sarcoma cells using THZ531 prominently synergized with ABT-888." (PMID 35163134, 2022). "Structure-activity relationship study of THZ531 derivatives found that CDK12/13 dual inhibitor BSJ-01-175 could treat Ewing’s sarcoma." (PMID 36463205, 2022). "This impact on the DNA repair proficiency of CDK12 is likely not limited to Ewing sarcoma." (PMID 34092037, 2021). "Likewise, inhibition of CDK12 resulted in synthetic lethality in Ewing sarcomas driven by the oncogenic fusion protein EWS‐FLI1, which encodes for a powerful transcription factor that reprogrammes the transcriptome of sarcoma cells." (PMID 34092037, 2021). "A notable example is THZ-531, an ATP-site-directed covalent inhibitor that irreversibly binds CDK12/13 and synergizes with PARP inhibitors in models of hepatocellular carcinoma and Ewing sarcoma." (PMID 41491919, 2026). "Collectively, these findings demonstrate that EWS/FLI1-driven tumors rely on CDK12-mediated DDR transcription, and that combined CDK12 and PARP inhibition represents a rational synthetic-lethal strategy in Ewing sarcoma." (PMID 41491919, 2026). "It was found that CDK12 inhibitors (THZ1 and THZ531) also impaired expression of DDR genes in Ewing sarcoma cells and sensitised them to treatment with PARPi." (PMID 34092037, 2021). "The molecule BSJ-01-175 is a novel potent CDK12/13 covalent inhibitor, showing high capacity in reducing RNAPII S2 phosphorylation, expression of BRCA1 and BRCA2 genes, and tumour growth of patient-derived xenograft of TC71 Ewing sarcoma cells." (PMID 39533070, 2025). "In particular, fusion-positive Ewing sarcoma cells (A673 and TC32) exhibit exquisite sensitivity to THZ531, a CDK12/13 inhibitor, resulting in the downregulation of the homologous recombination (HR) and DNA damage checkpoint genes, including BRCA1, ATR, FANCl, and FANCD2." (PMID 40760094, 2025). "Furthermore, CDK12 also lethally interacts with proto-oncogenes such as MYC and EWS/ FLI (Ewing sarcoma (ES) oncoprotein) and these interactions also provide an opportunity for a therapeutic target." (PMID 33868579, 2021). "The combination of CDK12 and PARP inhibitors is highly active in Ewing Sarcoma." (PMID 32570740, 2020). "CDK12 plays an important role in promoting cancer cell growth, especially in cancers driven by dysregulated transcription factors, such as cancers dependent on MYC (neuroblastoma) and the EWS–FLI1 fusion oncoprotein (Ewing sarcoma)." (PMID 32570740, 2020). "Genetic and pharmacologic suppression studies show that CDK12, not CDK13, is critical for the survival of Ewing sarcoma cells." (PMID 41491919, 2026).
breast tumors (10 papers, 2017 to 2025). "Some 5–15% of many tumors harbor structural changes in CDK12 which seems to render them susceptible to a tandem duplicator phenotype and, in breast tumors, to an aggressive “BRCAness” phenotype." (PMID 31259151, 2019). "Regarding other metabolic pathways, CDK12 overexpression in breast tumors promotes the serine-glycine synthesis pathway, rendering these neoplasms more susceptible to methotrexate." (PMID 40996961, 2025). "To assess the relevance of these findings to CDK12-induced mammary tumorigenesis in vivo, we reverted to the CDK12-KI/PyMT mouse breast tumor model." (PMID 35550508, 2022). "Consistently, in retrospective patient cohort studies and in patient-derived xenografts, CDK12-overexpressing breast tumors show positive response to methotrexate-based chemotherapy targeting CDK12-induced metabolic alterations, while being intrinsically refractory to other types of chemotherapy." (PMID 35550508, 2022). "Here, we provide extensive functional evidence that CDK12 is a primary oncogene, which, when overexpressed in the normal mammary epithelium, causes the formation of spontaneous breast tumors, in addition to actively cooperating in chemical carcinogen- or oncogene-induced breast tumorigenesis." (PMID 35550508, 2022). "Importantly, CDK12 overexpression has been documented in breast tumors." (PMID 29090014, 2017). "One of the summits in the breast tumor sample absent from the colon tumor sample corresponds to the bidirectional promoters of MED1 and CDK12, both of which have been shown to functionally cooperate with co-amplified ERBB2 in aggressive breast cancer." (PMID 39946483, 2025).
Fanconi anemia (8 papers, 2019 to 2024). Fanconi anemia (FA) is a hereditary DNA repair disorder characterized by progressive pancytopenia with bone marrow failure, variable congenital malformations and predisposition to develop hematological or solid tumors. "Genomic profiling should be performed by NGS panel that covers the potentially actionable targets in PC such as DNA damage repair (HRR, MMR and Fanconi anemia genes, and CDK12), phosphatidylinositol-3-kinase (PI3K), and RAS/RAF/MEK pathways." (PMID 35924163, 2022). "Among the DNA damage repair pathways, homologous recombination defects (HRDs) were found in 23.4% of cases, Fanconi anemia gene defect in 4.8%, CDK12 abnormality in 5.6%, and MMR gene defects in 4.3%." (PMID 35924163, 2022). "HRR and Fanconi Anemia genomic abnormalities have been associated with responses to PARP inhibitors and CDK12 mutations were associated in preclinical studies with immunotherapy sensitivity and in HRR, affecting DNA damage response genes." (PMID 31366128, 2019). "Other involved pathways were again cell cycle signaling (15%, CDK6, CDK12), Fanconi anemia/DNA repair (15%, FANCD2, NBN), and additionally peroxisome proliferator-activated receptor (PPAR) signaling (8%, PPARG) as well as discoid in domain receptor 2 signaling (8%, DDR2)." (PMID 34200508, 2021). "In vitro, CDK12 loss-of-function mutations and CDK12 inhibition (CDK12i) reduced the expression of HR-related genes, including BRCA1, ATR, and Fanconi-anemia pathway genes, due to premature cleavage and polyadenylation, leading to reduced capacity for HR repair." (PMID 32722408, 2020).
lung carcinoma (8 papers, 2014 to 2025). "CDK1 and CDK12 inhibition led to HR deficiency by decreasing HR repair proteins RAD51, BRCA1, and BRCA2 in lung cancer." (PMID 37370140, 2023). "It is known that the knockdown of CDK12 can inhibit the progression of the cell cycle of esophageal and lung cancer." (PMID 33628849, 2021). "Knockdown of CDK12 inhibited the proliferation of lung cancer and esophageal cancer cells." (PMID 36463205, 2022).
colon carcinoma (7 papers, 2023 to 2025). "Cancer stemness was suppressed by dinaciclib or THZ531 treatment, or knockdown of CCNK; hence, CDK12 inhibitors are potential chemotherapeutic agents against colon cancer." (PMID 38182897, 2024). "We show that selective targeting of CDK12 in colon cancer-derived cells activates P-TEFb via its release from the inhibitory 7SK snRNP." (PMID 37811895, 2023). "Additionally, the chemical inhibition of CDK12 (a downstream transcription CDK of PAF1C) suppressed colon cancer stemness." (PMID 38182897, 2024). "This research was primarily carried out in HCT116 and DLD-1 colon cancer cell lines, and while the basic functions of LEO1 and CDK12 in transcription are likely to be conserved, the effects of LEO1 mutations or CDK12 inhibition on target genes may differ in other cell types." (PMID 37205756, 2023).